TWIST1 (twist family bHLH transcription factor 1)
Diseases named in the same sentence as TWIST1 in open-access papers (continued):
Sharing a sentence is not in itself a finding about the gene and the disease.
glioma (53 papers, 2010 to 2026). A benign or malignant brain and spinal cord tumor that arises from glial cells (astrocytes, oligodendrocytes, ependymal cells). "Glioma cells migrate and invade when the lncRNA TWIST1, upon LINC00339 polymorphism, interacts with miR-539-5p, negatively impacting the miRNA for VM in an MMP-2 and MMP-14 dependent way." (PMID 37245177, 2023). "In human gliomas, increased Twist1 expression is associated with high tumor stage, and overexpressed Twist1 in a human glioma cell line significantly enhanced cell invasion." (PMID 30973923, 2019). "Here we used an orthotopic mouse glioma model of transplanted transformed neural progenitor cells (NPCs) to demonstrate the effects of Twist1 loss of function on tumorigenicity." (PMID 29296200, 2017). "In this regard, our studies on hGBM tissue grade IV specimens showed significant expression of Twist1 and Sox2, known mesenchymal and stemness related markers, respectively, indicating their association with glial tumor genesis and metastasis." (PMID 22184289, 2011). "Additionally, the current study revealed that the radiomic risk score was significantly positively correlated with glioma stem cell markers such as TWIST1 (R = 0.503, P < 0.001) and CD133 (R = 0.346, P = 0.016)." (PMID 30696801, 2019). "Twist1 has also been associated with increased malignancy of human glioma." (PMID 29296200, 2017). "Our present data indicate that both Sox2 and Twist1 expression escorts glial tumorigenesis and that their higher expression levels may be associated with grade IV glial tumors." (PMID 22184289, 2011). "As tumor migration has been found to be closely related to tumor relapse, we further analyzed the level of Twist1 in primary and recurrent gliomas." (PMID 35219305, 2022). "Mechanistically, NE mainly bound to ADRB and further increased the expression of Twist1 to induced mesenchymal-like phenotype of glioma cells." (PMID 35219305, 2022). "The result showed that the expression of Twist1 was higher in glioma samples than in control samples (Student’s t-test, p = 0.014)." (PMID 35219305, 2022). "Twist1 overexpression promoted glioma cells migration, while knockdown of Twist1 abolished the discrepancy in the migration ability between NE treated glioma cells and control cells." (PMID 35219305, 2022). "Twist1 overexpression facilitated the glioma cell migration, while knockdown of Twist1 abrogated the effect of NE on glioma cell migration." (PMID 35219305, 2022). "The result showed that Twist1 expression was up-regulated in the recurrent gliomas compared to the primary gliomas (Student’s t-test, p = 7.12e-09)." (PMID 35219305, 2022). "As reported in other literatures, the expression of Twist1 is closely regulated by the PI3K/AKT signaling pathway in glioma and many other tumors." (PMID 35219305, 2022). "Circ-ASB3 was shown to increase glioma cell proliferation, invasion, and migration in vitro via miR-543/Twist1 axis." (PMID 35492076, 2022). "Taken together, these results supported that knockdown of Twist1 inhibited glioma cells migration under NE treatment, indicating a regulative role of Twist1 in NE-mediated glioma cells migration." (PMID 35219305, 2022). "More recently, emerging evidence has shown that elevated expression of Twist1 was observed during the glioma cell invasion and migration." (PMID 35219305, 2022). "More experimental investigations will be required to clarify these contradictory data in order to improve our understanding on how Twist1 is regulated by TGF-β1 in U-87 MG glioma cells and likely its modulation by TGF-β1 in GBM growth." (PMID 35628507, 2022). "The analysis of the TCGA data set indicated that Twist1 was hyper-expressed in mesenchymal subtypes compared to proneural, neural and classical subtypes of glioma tumors (One-way ANOVA, p = 4.62e-04)." (PMID 35219305, 2022).
glioma (continued). "The signal pathway RNA and protein expression detection revealed that the circ-ASB3 and Twist1 gene expressions were significantly up-regulated while miR-543 gene expression was significantly down-regulated in high-grade glioma samples." (PMID 35492076, 2022). "Linc00339 inhibits the negative regulation of miR-539-5p on TWIST1 by competitively binding with miR-539-5p, enhances the ability of VM formation in glioma cells." (PMID 33542193, 2021). "Of significance, the process of epithelial-to-mesenchymal transition (EMT) in gliomas can be delayed by miR-361-5p targeting Twist1." (PMID 34321465, 2021). "LINC00339 also promoted glioma vasculogenic mimicry formation via regulating the miR-539-5p/TWIST1/MMPs axis." (PMID 32793467, 2020). "Epithelial‐mesenchymal transition is characterized by loss of epithelial markers (eg E‐cadherin) and gain of mesenchymal markers (eg N‐cadherin, β‐catenin, Twist1), and it has been considered to be an important regulator of the invasiveness of glioma cell." (PMID 32125767, 2020). "Our findings are in agreement with published report whereby loss of NF1 by shRNA promoted glioma cell invasion and upregulation of EMT markers such as vimentin, SNAI, TWIST1, ZEB1, and ZEB2." (PMID 30967630, 2019). "TWIST1 has been repeatedly investigated in adult glioma, in which its expression is correlated with higher tumor grade and poorer survival of patients." (PMID 29164272, 2018). "It was also reported that miR-361-5p inhibited epithelial-to-mesenchymal transition through targeting Twist1 in glioma cells." (PMID 29435149, 2018). "Mechanistically, this is attributed to the increased migratory and invasive capacities of glioma cells by TWIST1 activity." (PMID 29164272, 2018). "Analysis of TWIST1 mRNA expression in the publically available databases, REMBRANDT and ATCG, showed that TWIST1 was more highly expressed in GBM compared to lower grade gliomas." (PMID 29165393, 2017). "Major TGF-Beta-EMT inducing factors (RHOA, RAC1, ROCK2, CDC43 and LIMK1) and EMT transcription factors (TWIST1, SOX9, TRIM28 and SERP2) have among the highest risk scores in our glioma transcriptional model." (PMID 28916782, 2017). "Recent studies demonstrate that miR-33a is highly expressed in osteosarcoma, enhances osteosarcoma cell resistance to cisplatin by targeting Twist1, and promotes glioma-initiating cell self-renewal in glioma." (PMID 26507842, 2015). "Subsequent to the finding that glioma stemness was co-regulated by Twist1 and Sox2, normal neural stem cells that acquired glioma-like invasiveness through the combined FGF2 and BMP4 pathways were found to demonstrate EMT-related features." (PMID 25605251, 2015). "Regarding that EMT is closely associated with migration and invasion of cancer cells, we subsequently investigated the effect of OA on EMT processes of glioma cells by examining the changes in E-cadherin, N-cadherin, Vimentin and Twist1 expression." (PMID 23991044, 2013). "Expression levels of two other mesenchymal related proteins, N-cadherin and Twist1, consistently declined in the OA-treated glioma cells." (PMID 23991044, 2013). "It has been demonstrated that in gliomas TWIST-1 promotes cellular invasion through activation of mesenchymal and molecular changes, avoiding the typical pathway by using the cadherine switch." (PMID 24213322, 2012). "In conclusion, for the first time, we showed that interactive and co-regulatory role of Twist1 and Sox2 necessary to maintain glioma stemness was inhibited by hUCBSC." (PMID 22184289, 2011). "(Five hGBMs 2,4,5,6 and 7 of seven glioma specimens expressed variable levels of both Sox2 and Twist1)." (PMID 22184289, 2011). "In the present study, we show that malignant human grade IV gliomas display significant expression of Twist1 and Sox2." (PMID 22184289, 2011).
glioma (continued). "To evaluate this relationship, we examined seven tissue samples of grade IV gliomas (from surgical biopsy specimens) labeled with antibodies against Sox2 and Twist1." (PMID 22184289, 2011). "Our studies on glioma stem cells treatment with human umbilical cord blood derived- mesenchymal stem cells, showed down regulation of Twist1 and Sox2 proteins, apart from other mesenchymal stem cell markers." (PMID 22184289, 2011). "The glioma stem cells obtained from CD133+ cells demonstrated increased expression of Twist1 and Sox2 accompanied by significant increase in the mesenchymal markers such as N-cadherin, vimentin and β-catenin." (PMID 22184289, 2011). "Since tumor invasion is perhaps the major obstacle to improved outcome for patients with carcinomas and gliomas the elucidation of TWIST1 function in GBMs is potentially of great clinical importance." (PMID 20646316, 2010). "Together these results indicated the potential therapeutic relevance of TWIST1 inhibition for invasion and abrogation of glioma stem cell properties." (PMID 20646316, 2010). "Using well-characterized glioma stem cells we then tested the effect of TWIST1 inhibition on sphere-forming activity." (PMID 20646316, 2010). "We previously reported that TWIST1 is up-regulated in malignant gliomas and promotes glioma cell invasion of the SF767 glioma cell line in vitro." (PMID 20646316, 2010). "Together these results demonstrated an important role of TWIST1 in glioma invasion through activation of mesenchymal change and suggest its potential as a therapeutic target." (PMID 20646316, 2010). "The highly correlated expression of TWIST1 and mesenchymal target genes SNAI2 and FAP in human gliomas supported the clinical relevance of TWIST1 mesenchymal change." (PMID 20646316, 2010). "To confirm that putative TWIST1 targets play a role in glioma cell invasiveness, we overexpressed SNAI2 in SNB19 cells and found that SNAI2 was sufficient to increase SNB19 cell invasion 80%." (PMID 20646316, 2010). "Therapeutically, TWIST1 knockdown can lead to glioma regression." (PMID 37245177, 2023). "In conclusion, TWIST1 is a conserved EMT-TF transcriptionally regulated by JICD1 in gliomas." (PMID 38092725, 2023). "circ-ASB3 could enhance glioma malignancy via miR-543/Twist1 axis, resulting in the discovery of new biomarkers and possible therapeutic targets for these patients." (PMID 35492076, 2022). "In addition, the clinical analysis demonstrated that Twist1 was up-regulated in malignant gliomas and recurrent gliomas, and predicted a poor prognosis of glioma patients." (PMID 35219305, 2022). "Consistent with previous reports, we also proved that overexpression of Twist1 could promote glioma cells migration." (PMID 35219305, 2022). "The results of clone formation assay showed that in circ-ASB3 down-regulated glioma cells, the number of new cells obviously decreased, while in glioma cells combined with combined with miR-543 inhibition or Twist1 overexpression, the number of new cells correspondingly increased." (PMID 35492076, 2022). "The circ-ASB3/miR-543/Twist1 axis was discovered to be a possible regulatory pathway in glioma, circ-ASB3 could adsorb and targeted bind to miR-543, down-regulate miR-543 expression, thus release its targeted inhibition to Twist1." (PMID 35492076, 2022). "Our findings revealed that GSCs contained circ-ASB3 could accelerated proliferation, invasion, migration and inhibit apoptosis of glioma cells through miR-543/Twist1 pathway." (PMID 35492076, 2022). "But it is still unknown whether Twist1 is involved in the effect of NE on the migration of glioma cells." (PMID 35219305, 2022). "In the meantime, Twist1 protein content was obviously increased in high grade glioma samples." (PMID 35492076, 2022). "NE enhanced the migration ability of glioma cells through elevating the expression of Twist1." (PMID 35219305, 2022).
glioma (continued). "Moreover, our data revealed that Twist1 was up-regulated in malignant gliomas and recurrent gliomas, and predicted a poor prognosis of glioma patients." (PMID 35219305, 2022). "Then, we conducted a series of in vitro assays and found that circ-ASB3 could promote glioma progression by regulating miR-543/Twist1 axis." (PMID 35492076, 2022). "All these findings suggested that circ-ASB3 may enhance glioma malignant progression through miR-543/Twist1 axis." (PMID 35492076, 2022). "In summary, circ-ASB3 was significantly up-regulated in glioma stem cells, it could increase Twist1 expression by competitively inhibiting miR-543, thus promoting glioma malignant transformation." (PMID 35492076, 2022). "According to the results of apoptosis detection, in circ-ASB3 down-regulated glioma cells the percentage of apoptotic cells increased significantly, while in glioma cells combined with miR-543 inhibition or Twist1 overexpression, the percentage of apoptotic cells correspondingly decreased." (PMID 35492076, 2022). "The results of migration assay showed that in circ-ASB3 down-regulated glioma cells the transversely-migrated cells evidently decreased, while in glioma cells combined with miR-543 inhibition or Twist1 overexpression, the number of transversely-migrated cells correspondingly increased." (PMID 35492076, 2022). "The role of Twist1 in regulating the migration of glioma cells was further explored." (PMID 35219305, 2022). "The results of invasion assay showed that in circ-ASB3 down-regulated glioma cells the vertically-migrated cells decreased significantly, while in glioma cells combined with miR-543 inhibition or Twist1 overexpression, the number of vertically-migrated cells correspondingly increased." (PMID 35492076, 2022). "The results showed that the mRNA expression levels of Twist1, Twist2, Zeb1, Zeb2 and Slug2 maintained significantly negative correlations with the mRNA expression levels of Presenilin1 in gliomas of all WHO grades, but the relationships were not significant between Presenilin1 and Slug1." (PMID 34781973, 2021). "Twist1 is a basic helix-loop-helix (bHLH) transcription factor that is essential for normal vertebrate development, but is overexpressed in cancers of the breast, prostate and stomach, including melanomas, gliomas and osteosarcomas." (PMID 32337580, 2020). "Importantly, one study found that a reduction of TWIST1 expression in glioma stem cells, achieved by co-culturing these stem cells with mesenchymal stem cells, induces a mesenchymal-to-epithelial transition (MET), the inverse process of EMT, in these cells." (PMID 29164272, 2018). "We and others have reported that TWIST1 (TW), a bHLH transcription factor (TF) and master regulator of epithelial‐to‐mesenchymal transition (EMT), is associated with increased glioma grade and promotes invasion and glioma stem cell (GSC) phenotypes." (PMID 29754406, 2018). "Twist1 enhances glioma invasion in concert with mesenchymal changes." (PMID 23826359, 2013). "Although earlier studies have indicated the independent expression of Sox2 and Twist1 in different cancers including glioma, the functional relationship of Sox2 and Twist1 together in GSC remains unknown." (PMID 22184289, 2011). "By constructing GSCs specific circRNA-miRNA-mRNA regulatory network, exploring mRNA function, consulting relevant literatures and proceeding RT-PCR verification, we found that circ-ASB3/miR-543/Twist1 signal pathway may be closely related to the regulation of glioma biological characteristics." (PMID 35492076, 2022). "Finally, the clinical significance of Twist1 was explored among three public glioma datasets." (PMID 35219305, 2022).
glioma (continued). "In addition, the overall survival (OS) analysis demonstrated that Twist1 high expression in gliomas predicted short survival of patients by analyzing the TCGA database (Kaplan-Meier method, p = 0.02 & 0.026, respectively) and CGGA datebase (Kaplan-Meier method, p = 7.12e-09)." (PMID 35219305, 2022). "Therefore, the driver mutational context in which Twist1 functions may need to be taken into account when evaluating mechanisms of action and developing therapeutic approaches to target Twist1 in human gliomas." (PMID 29296200, 2017). "To determine whether inhibition of TWIST1 expression may have therapeutic relevance we investigated the effects of TWIST1 knockdown on cell invasion and glioma stem cell proliferation as well as tumor sphere formation using sequence-specific shRNA lentiviral constructs." (PMID 20646316, 2010). "SETD6 mRNA levels in patients with glioma are positively correlated with those of several transcription factors that are known to be involved in EMT, such as TWIST1." (PMID 40102573, 2025). "Tumourigenesis and histogenesis of gliomas are modulated by ING5, a tumour suppressor; its overexpression decreases the level of Snail, Slug, Twist1, ZEB1 and ZEB2 in glioma cells and inhibited tumour growth in a xenograft mouse model." (PMID 37239035, 2023). "The risk score was positively correlated to the oncogenes S100A4, TWIST1, CDH2, and POSTN, which were critically involved in glioma migration and invasion." (PMID 32733879, 2020). "Transfection of RIOK2 siRNAs significantly inhibited glioma cell migration and invasion and down‐regulated the expression of MMPs (MMP2 and MMP9) and mesenchymal markers (N‐cadherin, β‐catenin, Twist1, fibronectin, ZEB‐1) in glioma cells." (PMID 32125767, 2020). "Here, we found that overexpressing RIOK2 elevated the expression of N‐cadherin, β‐catenin, Twist1, fibronectin and ZEB‐1, whereas the miR‐4744 mimics treatment showed the opposite effects in glioma cells." (PMID 32125767, 2020). "Several EMT markers or inducers, including Twist1, ZEB1, and SNAIL, have been reported to enhance glioma stemness, leading to cancer progression and therapeutic resistance." (PMID 25605251, 2015). "Compared to normal brain controls, the mean TWIST1, SNAI2 and FAP expression were all up-regulated in the most malignant grade IV gliomas compared with grade II and III tumors (p = 0.022, p = 0.0014, p = 0.005, respectively)." (PMID 20646316, 2010). "In a set of 39 human glial neoplasms using quantitative RT-PCR we found a significant correlation between TWIST1 and SNAI2 (r = 0.72; p = 0.001) and TWIST1 and FAP alpha (r = 0.57, p = 0.001) message levels." (PMID 20646316, 2010). "The clinical relevance of identified putative TWIST1 targets was established through correlation between TWIST1, SNAI2 and FAP expression levels in 39 human gliomas of different grades." (PMID 20646316, 2010). "Similarly, treatment with cyanidin was shown to suppress glioma stem cell (GSC) viability via downregulating β‐catenin and Wnt target genes such as MYC and TWIST1." (PMID 40589077, 2025). "To explore the clinical significance of Twist1, we analyzed the levels of Twist1 in glioma tissues and normal tissues, different World Health Organization (WHO) tumor grades and different subtypes using multiple datasets." (PMID 35219305, 2022). "Furthermore, the biological effect of NE on glioma cells migration was attributed to the binding with ADRB and the regulation of Twist1 expression." (PMID 35219305, 2022).